SOD2 (superoxide dismutase 2)
Diseases named in the same sentence as SOD2 in open-access papers (continued):
Sharing a sentence is not in itself a finding about the gene and the disease.
fibrosis (10 papers, 2018 to 2025). the formation of excess fibrous connective tissue in an organ or tissue in a reparative or reactive process. "The gene expressions of superoxide dismutase (SOD1; SOD2) and glutathione peroxidase (GPx1) were evaluated using real-time PCR in advanced fibrosis (AF: F3F4) in patients with PBC." (PMID 38671835, 2024). "Twenty-four haplotype combinations were generated from the four selected encoding genes (-627 IL10, -400 MTP, 1183 SOD2, and APOE) among Mild and Severe fibrosis groups." (PMID 33924242, 2021). "However, the activation of SIRT3 can inhibit cardiomyocyte apoptosis and alleviate cardiac fibrosis by reducing ROS, enhancing the activities of antioxidant enzymes such as SOD2, and improving mitochondrial function." (PMID 40943150, 2025). "Strikingly, we identified a negative correlation between the expression level of SOD2 and the grade of BM fibrosis in PMF, suggesting that ROS accumulation caused by SOD2 reduction could favor the TGF‐β1‐driven progression of fibrosis." (PMID 30259659, 2018). "The polymorphism C47T of the SOD2 gene, encoding for manganese superoxide dismutase, is associated with a reduction of activity of this enzyme resulting in an increased ROS production and a high susceptibility to developing NASH and advanced fibrosis in NAFLD." (PMID 29991976, 2018).
oral cancer (10 papers, 2012 to 2024). "Specifically, TCAM1 has been associated with the HPV status of patients with head and neck squamous cell carcinomas; another example is SOD2 that has been implicated with the progression and metastasis of oral cancer." (PMID 23173873, 2012). "Moreover, SOD2 is suggested to be a prognostic biomarker of oral cancer malignancy because SOD2 overexpression is associated with lymph node metastases." (PMID 37108069, 2023). "Thus, the published studies suggest that elevated tumor SOD2 levels are associated with enhanced invasiveness of oral cancer." (PMID 24348785, 2014). "Few studies on SOD2 SNPs have been reported in association with oral cancer." (PMID 24348785, 2014). "Therefore, in the present study it was hypothesized that the polymorphic variants of SOD2 may be involved in the development and prognosis of oral cancer." (PMID 24348785, 2014). "A number of studies have demonstrated that the activity and expression of SOD2 changes significantly in patients with oral cancer, and either promotes or suppresses tumor formation." (PMID 24348785, 2014). "Since WFA induces MitoSOX generation in oral cancer cells, mitochondrial SOD2 expression may play a vital role in WFA-induced oxidative stress." (PMID 34209212, 2021). "Western blotting revealed that silibinin downregulated SOD1 and SOD2 and triggered the JNK/c-Jun pathway in oral cancer cells." (PMID 37476191, 2023).
squamous cell carcinoma (10 papers, 2013 to 2025). A carcinoma arising from squamous epithelial cells. "The existence of a significantly higher risk in smokers carrying one or both variant SOD2-Val alleles was also confirmed in a study of patients with squamous cell carcinoma of the oral cavity." (PMID 36676755, 2023). "Conversely, in lung, colorectal, and squamous cell carcinoma of the oral cavity, an increased risk was registered in individuals carrying the variant SOD2-Val allele." (PMID 36676755, 2023). "In conclusion, this study showed that a high SOD2 expression is associated with a very pessimistic prognosis for squamous cell carcinoma of the uterine cervix IIIB." (PMID 34062984, 2021). "SOD2 expression predicts regional lymph node metastasis in usual type squamous cell carcinomas of the penis." (PMID 25745358, 2015). "A previous study showed that SOD2 is strongly expressed in cervical intraepithelial neoplasia grade 3 and squamous cell carcinoma compared with non-neoplastic tissues." (PMID 40244057, 2025). "The present study investigated SOD2 protein expression and the presence of hr-HPV types in 297 cervical samples including non-neoplastic tissue, cervical intraepithelial neoplasia grade 3 (CIN3), squamous cell carcinoma (SCC) and adenocarcinoma (ADC)." (PMID 29774090, 2018). "Moreover, SOD2 is strongly expressed in cervical intraepithelial neoplasia grade 3 and squamous cell carcinoma compared with non-neoplastic tissues." (PMID 40244057, 2025).
chronic obstructive pulmonary disease (9 papers, 2012 to 2025). A chronic and progressive lung disorder characterized by the loss of elasticity of the bronchial tree and the air sacs, destruction of the air sacs wall, thickening of the bronchial wall, and mucous accumulation in the bronchial tree. "Similar to the effects of catalase, PC-specific overexpression of both the cytosolic and mitochondrial isoforms of SOD (SOD1 and SOD2) increased the incidence of cardiac arrhythmia and caused constriction of the heart tube." (PMID 24656823, 2014). "Notably, genetic knockdown of the mitochondrial antioxidant enzyme SOD2 in iAMs and Drosophila induced MitoOxS and demonstrated that MitoOxS plays a causal role in cardiac arrhythmia and dysfunction." (PMID 41462644, 2025). "Moreover, there are several types of SOD2 mimetics that have a positive effect on the inflammatory response of lung epithelial cells in preclinical models of chronic obstructive pulmonary disease." (PMID 35361071, 2022).
esophageal cancer (9 papers, 2016 to 2025). A primary or metastatic malignant neoplasm involving the esophagus. "Studies on gastric and esophageal cancers have shown that SOD2 activity is stronger in these cancers than in the normal mucosa." (PMID 40244057, 2025). "Co-expression of ANXA2 with HOXA13 and SOD2 has also been found to play a prognostic role in esophageal cancer." (PMID 38658569, 2024). "The upregulation of SOD2 by TNF-α was inhibited by blocking the NF-κB pathway, suggesting that SOD2 via the NF-κB signaling pathway contributes to the proliferation of esophageal cancer cells." (PMID 36672191, 2023). "The TNF-α-mediated upregulation of SOD2 is involved in cisplatin resistance in esophageal cancer." (PMID 36672191, 2023).
hearing loss (9 papers, 2015 to 2025). "Previous studies have proved that upregulation of SOD2 can resist oxidative stress and attenuate hearing loss." (PMID 37061707, 2023). "The present work demonstrates that decreasing the methylation of SOD2 suppresses the mtDNA4834 deletion in MCs under oxidative stress and provides potential insights to the intervention therapy of aging-related hearing loss." (PMID 31465718, 2020). "Sod2, catalase, and peroxiredoxin which contains free radicals have been known to have an essential role in the cochlea in noise-induced hearing loss (NIHL)." (PMID 29220389, 2017). "Currently, there is limited information about the relationship between manganese superoxide dismutase (sod2) c47t polymorphism and susceptibility to noise-induced hearing loss (NIHL)." (PMID 27161188, 2017). "Furthermore, transgenic mice overexpressing SOD2 were protected against aminoglycoside-induced hearing loss, which is also mediated by ROS." (PMID 27161188, 2017). "Genetic variants in SOD2 and MGST3 are proposed as mechanistically associated with cisplatin-induced hearing loss." (PMID 37568739, 2023). "Moreover, C57BL/6J mice fed a high-fat and high-fructose diet for 12 weeks had significant hearing impairment, as well as increased levels of ROS and hair cell death due to reduced levels of pAKT and superoxide dismutase 2 (SOD2) in the cochlea." (PMID 40507055, 2025). "Variation in the gene encoding for MnSOD, SOD2, has been implicated in noise-induced hearing loss but has not been explored in the context of treatment-related ototoxicity." (PMID 26400460, 2015).
leukemia (9 papers, 2013 to 2025). A malignant (clonal) hematologic disorder, involving hematopoietic stem cells and characterized by the presence of primitive or atypical myeloid or lymphoid cells in the bone marrow and the blood. "To validate that loss of SOD2 sensitizes leukemia cells to asparaginase, we first induced an shorth hairpin RNA (shRNA)-mediated knockdown of SOD2 (shSOD2), which resulted in efficient gene silencing as assessed by RT-qPCR and western blot." (PMID 40131931, 2025). "Of note, inhibition of SOD2 or UBRs highly sensitized drug-resistant human leukemia PDXs to asparaginase." (PMID 40131931, 2025). "In leukemia, inhibition of SOD2 sensitizes cells to asparaginase treatment, demonstrating its therapeutic potential." (PMID 40131931, 2025). "Intriguingly, inhibition of SOD2 or UBRs highly sensitized drug-resistant patient-derived xenograft (PDX) leukemia specimens to asparaginase." (PMID 40131931, 2025). "Recently, it was demonstrated that clinically doxorubicin-resistant leukemia cells overexpressed SOD2." (PMID 39408587, 2024). "Increases in SOD1 and SOD2 have been observed in blood samples from patients with various types of leukemia." (PMID 23431283, 2013). "Therefore, to prevent oxidative stress and cytotoxic effects as a result of increased TCA and OXPHOS in leukemic cells, the presence of stroma led also to increased SOD2 expression, decreased ROS production and oxidation in leukemia cells." (PMID 41331927, 2025). "Resistant leukemia cells exhibited an abundance of ARNT and also followed upregulation of SODs (SOD2), nuclear factor erythroid 2-related factor 2 (Nrf2) transcript, and intracellular glutathione concentration." (PMID 24921657, 2014). "Knockdown of SOD2 induced a significant reduction in viability upon treatment with asparaginase but did not sensitize leukemic cells to other commonly used leukemia chemotherapeutic agents." (PMID 40131931, 2025).
lymph node metastasis (9 papers, 2005 to 2025). "Statistical analysis revealed that the reduced SOD2 expression in primary tumor tissue is associated with lymph node metastasis in both TSCC patient cohorts examined." (PMID 20618948, 2010). "In addition, higher SOD2 expression is associated with presence of lymph node metastasis in penile cancer." (PMID 35468924, 2022). "Our study suggested that the deregulation of SOD2 in TSCC has potential predictive values for lymph node metastasis, and may serve as a therapeutic target for patients at risk of metastasis." (PMID 20618948, 2010). "The SOD2 mRNA level in primary TSCC tissue is reversely correlated with lymph node metastasis in the first TSCC patient cohort." (PMID 20618948, 2010). "The SOD2 protein level in primary TSCC tissue is also reversely correlated with lymph node metastasis in the second TSCC patient cohort." (PMID 20618948, 2010). "Interestingly, the two cases in which lymph node metastasis was observed when tumor depth was less than 5 mm had positive SOD2 immunoexpression." (PMID 25745358, 2015). "Using exploratory logistic regression we observed that SOD2 expression in more than 50% of the cells was an independent predictive factor of lymph node metastasis as were other well documented clinical-pathologic variables such as palpable suspicious nodes, tumor depth >5 mm and perineural invasion." (PMID 25745358, 2015). "This study investigated whether SOD1 and SOD2 expression in OPC affects primary tumor progression, lymph node metastasis, stage, and overall survival (OS)." (PMID 40244057, 2025). "This study demonstrated that SOD2 expression is a prognostic factor for OS in OPC, independent of primary tumor size or lymph node metastasis." (PMID 40244057, 2025).
metastatic disease (9 papers, 2012 to 2022). "It is believed that loss of SOD2 expression propagates early progression of metastatic diseases, while evidence shows that SOD2 levels increase in many tumors as progression goes from the early to late stage of the disease progression." (PMID 32585852, 2020). "In contrast, SOD2 levels are commonly increased in advanced cancer tissues, especially in metastatic tumors, when compared to benign counterparts." (PMID 34062984, 2021). "The highest increase in SOD2 expression (0.21) is observed in undifferentiated anaplastic carcinoma, a highly aggressive metastatic tumor." (PMID 29478325, 2019). "While antioxidant therapy is clearly an undesirable approach in metastatic disease, pro-oxidant intervention with the combination of targeting the mechanisms that regulate antioxidants may be a beneficial strategy for tumor types that display enhanced SOD2 activity." (PMID 29099803, 2017). "In contrast, in another study that investigated patients with initially non-metastatic disease, SOD2 rs4880 SNP was not reported to contribute to overall survival." (PMID 36295574, 2022).
osteoarthritis (9 papers, 2011 to 2025). A noninflammatory degenerative joint disease occurring chiefly in older persons, characterized by degeneration of the articular cartilage, hypertrophy of bone at the margins and changes in the synovial membrane. "Reduction in GPx and other anti-oxidant enzymes, such as superoxide dismutase 2 (SOD2) occurs in osteoarthritis and could be linked to the further reduction in oxygen levels occurring in osteoarthritis (OA)." (PMID 23850530, 2013). "From the analysis of the degenerative cartilage in osteoarthritis patients, a pathological relationship between SOD2 downregulation and cartilage degeneration has been observed." (PMID 31940867, 2020). "However, the protective and regenerative effects of SOD2 related to osteoarthritis have not been fully elucidated." (PMID 31940867, 2020). "In addition, downregulation of SOD2 expression was described in osteoarthritis, and anti-TPI antibodies have been identified in several autoimmune conditions, including neuropsychiatric systemic lupus erythematosus (SLE), and in osteoarthritis." (PMID 21569507, 2011). "The role of SIRT4 in RA has not been studied, but SIRT4 can affect osteoarthritis through a variety of inflammatory factors, such as TNFα and IL-6, and the effect of SIRT4 on oxidative stress has also been proven the increased expression of SIRT4 can up-regulate SOD1, SOD2, and catalase." (PMID 37238636, 2023).
preeclampsia (9 papers, 2009 to 2025). Preeclampsia is a hypertensive disorder of pregnancy that is characterized by new-onset hypertension with proteinuria presenting after 20 weeks of gestation, and depending on mild or severe forms may initially present with severe headache, visual disturbances, and hyperreflexia. "Similarly, the expression of mtROS detoxifying enzymes, including the mitochondrial uncoupling protein 1 (UCP-1) and superoxide dismutase 2 (SOD2) are reduced in models of preeclampsia." (PMID 34196872, 2021). "Indeed, mitochondrial function appears to be differentially regulated in preeclampsia subtypes (i.e., early-onset vs. late-onset) and mitochondrial adaptations including upregulated SOD2 activity play a paramount role in determining successful outcomes in preeclamptic pregnancies." (PMID 33916770, 2021). "In particular, the failure to upregulate SOD2 expression towards GD18 observed in SHRSP placentas may be indicative of an underlying mitochondrial dysfunction, which is becoming increasingly recognized as a mechanism involved in preeclampsia pathogenesis." (PMID 33916770, 2021). "These compensatory changes, along with the increase in SOD1 and SOD2 reported herein, may impart a protective effect on the placenta and the developing fetus in response to additional stressors, such as maternal obesity or preeclampsia." (PMID 32628362, 2020). "The literature supports consistent changes in ApoB, Sod2, and EML4 trends with the results of this study, confirming a potential relationship between the therapeutic effects of SA on preeclampsia and the PI3K/Akt/eNOS pathway." (PMID 40717981, 2025). "Incubation with preeclampsia plasma induced a significant increase in SOD1 gene expression (1.32 ± 0.10 fold, n = 8, P < 0.05), SOD2 gene expression (1.35 ± 0.21 fold, n = 8, P < 0.05) and HO-1 gene expression (1.82 ± 0.42 fold, n = 8, P < 0.05) respectively compared to uncomplicated pregnancy." (PMID 27604418, 2016).
renal fibrosis (9 papers, 2018 to 2025). A final common manifestation of a wide variety of chronic kidney diseases characterized by glomerulosclerosis and tubulointerstitial fibrosis. "Notably, SOD2 supplementation (application of SOD2 mimetics or exogenous transfection of SOD2 plasmid) effectively alleviated endothelial injury and renal fibrosis exacerbated by LONP1 deficiency." (PMID 41275592, 2025). "While the expression of SOD2, an antioxidant enzyme, can protect against chronic kidney injury and renal fibrosis by reducing oxidative stress in renal tubular cells." (PMID 38270638, 2024). "SOD2 is a widely known antioxidant gene that reduces oxidative stress and has protective functions against renal fibrosis." (PMID 36499744, 2022). "Taken together, these results indicate that PARK7 protects against chronic kidney injury and renal fibrosis by inducing SOD2 to reduce oxidative stress in tubular cells." (PMID 34093596, 2021). "Collectively, these findings suggest that PARK7 may protect against chronic kidney injury and renal fibrosis by inducing SOD2 and reducing ROS and oxidative stress." (PMID 34093596, 2021). "Mechanistically, we showed that during renal fibrosis, PARK7 accumulated in the nucleus in renal tubular cells, and positively regulated expression of the antioxidant enzyme SOD2." (PMID 34093596, 2021). "In the present study, by using a unilateral ureteric obstruction (UUO)-induced mouse model of renal fibrosis, and culturing renal TECs exposed to TGFB1, we demonstrated that PARK7 protects against renal TIF and related kidney injury by inducing SOD2 and scavenging ROS." (PMID 34093596, 2021).
steatosis (9 papers, 2014 to 2023). Increased lipid within the cytoplasm of cells. "Further than the PNPLA3 and the TM6SF2 SNPs, we therefore tested the rs3750861 KLF6, the rs13412852 LPIN1, and the rs4880 SOD2 SNPs, which have demonstrated associations with fibrosis, steatosis and fibrosis, and again fibrosis, respectively, in previous studies on NAFLD patients." (PMID 29732362, 2018). "Meanwhile, the content of CAT and the mRNA expression level of Sod2 in the steatosis LO2 cells decreased compared with the normal control and the taurine prevention groups, indicating an antioxidant capacity of taurine on both the FLHS hens and the steatosis LO2 cells." (PMID 37373507, 2023).